IL18 (interleukin 18)
Diseases named in the same sentence as IL18 in open-access papers (continued):
Sharing a sentence is not in itself a finding about the gene and the disease.
endometriosis (20 papers, 2012 to 2026). The growth of functional endometrial tissue in anatomic sites outside the uterine body. "The findings suggest that elevated IL-18 in peritoneal fluid is associated with minimal-to-mild stages of endometriosis." (PMID 39767772, 2024). "Endogenous IL-18, which exerts concentration-dependent effects on the endometrium, acts as a local immune modulator crucial for normal endometrial function and is implicated in pathologies such as adenomyosis, endometriosis, and PCOS." (PMID 41516408, 2026). "Moreover, invalid IL-1β and IL-18 maturation by interleukin-1 converting enzyme (ICE) may be an important pathogenic factor in endometriosis." (PMID 23843796, 2013). "The results showed that IL-18 levels were significantly higher in women with untreated endometriosis (91.1 pg/mL) compared to controls (59.4 pg/mL)." (PMID 39767772, 2024). "One study aimed to measure IL-18 concentrations in the serum and peritoneal fluid of infertile women with endometriosis." (PMID 39767772, 2024). "Elevated IL-1β and IL-18 levels are seen in follicular fluid of endometriosis patients undergoing ovarian stimulation." (PMID 39769450, 2024). "They found that IL-1β and IL-18 levels were elevated in the follicular fluid in the endometriosis group, compared to the non-endometriosis group." (PMID 39769450, 2024). "IL-18 is a major regulator of the immune response process in a wide range of cells that decreases in both eutopic and ectopic endometrium in endometriosis." (PMID 39767772, 2024). "In the present study, IL-6, IL-8, IL-10, IL-18, IL-23, IFN-α2 and MCP-1, which are associated with endometriosis and considered to be exacerbating factors in endometriosis, were significantly lower in the treated group." (PMID 37629072, 2023). "In PF of endometriosis patients compared to controls, three pro-inflammatory cytokines (IL-6, IL-8 and IL-18) were significantly differently expressed." (PMID 36902452, 2023). "In PF of endometriosis patients, we found Interleukin 18 (IL-18) to be decreased, yet Interleukin 8 (IL-8) and Interleukin 6 (IL-6) to be increased." (PMID 36902452, 2023). "Suppression of IL-18 in women with endometriosis contributes to decreased natural killer (NK) cell activity which enhances the opportunity for escaping immune elimination in ectopic endometrium, resulting in survival and growth of ectopic endometrial implants." (PMID 36354688, 2022). "The elevation of peritoneal IL-18 was found in endometriosis patients with macrophage infiltration and COX-II induction, leading to prostaglandins production, and eventually causing pain." (PMID 36354688, 2022). "We found a significant induction of IL-16 in PM and IL-18 in PBMC isolated from patients with endometriosis." (PMID 35565370, 2022). "In addition, the concentration of IL-18 in the peritoneal fluid was significantly lower in patients with endometriosis than in those without endometriosis, suggesting IL-18 might play a pathogenic role in the formation of endometriosis." (PMID 31639028, 2019). "Our findings are consistent with the relationship between IL-18 and endometriosis identified in other studies." (PMID 31639028, 2019). "Additionally, women with early-stage endometriosis had higher IL-18 levels than controls, whereas those with advanced stages did not." (PMID 39767772, 2024). "However, a positive correlation was observed between serum and peritoneal IL-18 levels in the endometriosis patients (r = 0.794, p = 0.0001)." (PMID 39767772, 2024). "The data published regarding IL-18 expression in endometriosis patients show discrepant results." (PMID 36902452, 2023). "A prospective, multicenter and controlled trial suggested that QUF could prevent the recurrence of endometriosis and decrease the serum levels of cancer antigen 125 (CA-125) and interleukin 18 (IL-18)." (PMID 35130311, 2022). "In addition, the cytokines IL-1α, IL-6, IL-8, IL-18, and TNFα have been found to increase in endometriosis consistently." (PMID 35628423, 2022).
endometriosis (continued). "Moreover, the preclinical study has proved its effect of treating endometriosis by significantly reducing rat serum CA-125 levels and IL-18 in peritoneal fluid, and increasing the level of IL-13 in peritoneal fluid." (PMID 35250579, 2022). "In contrast, IL-18 has been reported to affect endometriosis negatively." (PMID 36354688, 2022). "Some studies demonstrated a significantly lower concentration of IL-18 in the peritoneal cavity of women with endometriosis, which may indicate a deterioration of the Th1 response in the pathogenesis of endometriosis." (PMID 36354688, 2022). "In a previous study, down-regulation of ectopic and eutopic endometrial IL-18 was found in patients with endometriosis, indicating that IL-18 might participate in the process of endometriosis." (PMID 36354688, 2022). "The findings did not support the hypothesis that IL-18 levels are associated with infertility in women with minimal or mild endometriosis." (PMID 39767772, 2024). "The alterations of IL-18 system may participate in the pathologic process of endometriosis." (PMID 36354688, 2022). "Thus, the role of IL-18 in endometriosis remains controversial." (PMID 31507610, 2019). "Thus, surgical removal of endometriotic lesions might stimulate the production of IL-18 in the FF of women with endometriosis." (PMID 31639028, 2019). "Granulosa cells from women with endometriosis show elevated levels of the NLRP3 inflammasome and increased IL-1β and IL-18 in follicular fluid, contributing to infertility." (PMID 40508002, 2025). "Alpha-lipoic acid has been shown to prevent endometriosis by preventing the NLRP3-mediated release of IL-1β and IL-18." (PMID 39769450, 2024). "The downregulation of miR-138 expression enhances inflammation in endometriosis by elevating levels of TNF-α, IL-1β, IL-6, and IL-18 through the activation of the NF-κB signaling pathway and VEGF." (PMID 39001478, 2024). "On the contrary, overexpression of IL-18 in peritoneal fluid and IL-18-induced COX-II in peritoneal monocytes are reported in endometriosis patients; moreover, IL-18 level is higher in patients with minimal- to mild-stage peritoneal endometriosis." (PMID 36354688, 2022). "The trends of increased levels of IL-16, IL-18, IL-1β and IFNγ were seen both in PM and PBMC in endometriosis patients." (PMID 35565370, 2022). "Extracts of S. miltiorrhiza have also shown promise in treating endometriosis by markedly reducing the serum levels of CA125 and the levels of IL-18 and TNF-α, by significantly increasing the levels of IL-13 in the peritoneal fluid in a rat model." (PMID 30402122, 2018). "Interestingly, increases in IL-17A, IL18, TNFSF13B, and TNF signaling have all been previously identified in endometriosis conditions." (PMID 35682747, 2022). "Several groups reported that IL-18 concentrations were down-regulated in peritoneal fluid of patients with endometriosis, but other groups did not observe this decrease." (PMID 31507610, 2019). "Higher follicular MIP-1α and CD44(v6) were found to correlate with polycystic ovary syndrome, IL-23, INF-γ, and TNF-α with endometriosis, higher CD44(v6) but lower IL-β and INF-α correlated with tubal factor infertility, and lower levels of IL-18 and CD44(v6) characterized unexplained infertility." (PMID 22007253, 2012). "We therefore hypothesize that surgical intervention might facilitate the expression of IL-18, which may be beneficial to the treatment of endometriosis, but does not improve the quality of oocytes." (PMID 31639028, 2019).
hemophagocytic lymphohistiocytosis (20 papers, 2013 to 2026). "For example, IL-1β has been reported to be associated with systemic symptoms such as fever; IL-6, with arthritis and typical skin rash; and IL-18, with hemophagocytic syndrome and liver injury." (PMID 36494453, 2022). "A study on hemophagocytic lymphohistiocytosis (HL), a prototypical hyperinflammatory disease, suggests that IL-18 and IL-10 may collectively promote the onset of a hyperinflammatory state." (PMID 37112918, 2023). "Similar elevation of serum IL-18 and susceptibility to MAS/hemophagocytic lymphohistiocytosis (HLH) have been reported in monogenic diseases such as X-linked inhibitor of apoptosis deficiency (i.e., X-linked lymphoproliferative syndrome type 2) and NLRC4-associated autoinflammatory disease." (PMID 35958573, 2022). "IL-18 induces a T helper (Th) 1 response and affects the secretion of INF-γ by cytotoxic CD8+ and NKs and it has been suggested that it plays a major role in the pathogenesis of reactive hemophagocytic lymphohistiocytosis." (PMID 39335580, 2024).
parasitemia (20 papers, 2012 to 2025). "IL-1β rs1143634 is notably associated with patient parasitemia, whereas IL-18 rs5744256 appears to play a protective role against anemia development." (PMID 39548522, 2024). "Moreover, IL-18 levels at inclusion were significantly associated with disease severity and the degree of parasitemia, as assessed by qPCR." (PMID 34663245, 2021). "NLRP3 was also thought to take part in T. gondii sensing by inducing interleukin 18 (IL-18), which was shown to be important for restricting parasite infection." (PMID 40075497, 2025). "Different haplotypes of IL6 gene or IL6R genes have been related to IL-6 and other cytokine serum levels in humans, including IL-2, IL-8 and IL-18 cytokines, and with the severity or protective effect of the infectious disease, including parasitic diseases." (PMID 36759910, 2023). "IL-18 and IL-18bp levels were related to disease severity and parasitemia as assessed by quantitative P. falciparum PCR analyses." (PMID 34663245, 2021). "Interleukin 18 is a pro-inflammatory cytokine and is key to promoting the production of interferon-gamma by NK cells against viral, fungal, bacterial and parasitic infections." (PMID 33013844, 2020). "Our data support a protective role of IL17A AA, IL18 AA, and IL1B TC genotypes against development/progression of cardiomyopathy and a modulatory effect of the IL6 CG genotype on the risk of parasitemia in Chagas disease." (PMID 33193300, 2020). "We observed on day 5 of parasite infection circulating IL-18 was significantly elevated in TLR11-/- mice compared to both WT and TLR11xCasp1/11-/- mice." (PMID 31194844, 2019). "Our results revealed administering IL-18 to TLR11xCasp1/11-/- mice during parasite infection dramatically augmented the frequency and absolute numbers of CD4+IFN-γ+ T cells both locally in the peritoneum and in the spleen, compared to non-treated controls." (PMID 31194844, 2019). "The transcript level of IL-18 in host cells was decreased during WT parasite infection but increased during PbMLFK-KO parasite infection." (PMID 27995998, 2016). "Cytokines of the IL-23/IL-22/IL-18 axis are pivotally involved in host defence and in mediating and regulating inflammatory immune responses upon bacterial and parasitic infection." (PMID 27385977, 2016). "However, the mixed generation of anti-inflammatory (IL-10) and pro-inflammatory (IL-18) immune mediators can negatively interfere with the activation of the cellular immune response, favoring parasite infection." (PMID 38474410, 2024). "Firstly, during the innate response, T. gondii infection triggers the production of inflammatory cytokines IL-1β, IFNα/β, IL-6, IL-12, IL-15, and IL-18, driving NK cell production of IFNγ, resulting in early control of parasite infection by targeting intracellular parasites." (PMID 37018796, 2023). "Interestingly, a recent paper showed that IL-18-MyD88 signaling is critical in expanding CD4+IFNγ+ T cells during parasitic infection." (PMID 34093543, 2021). "Therefore, since TLR11xCasp1/11-/- mice have intact IL-18R signaling, we examined if exogenous IL-18 administered to TLR11xCasp1/11-/- mice during parasite infection would be sufficient to restore CD4+ TH1-derived IFN-γ responses." (PMID 31194844, 2019). "We observed that deficiency on TNF-α and IL-18 secretion did not have impact on parasitemia and animal survival." (PMID 22509418, 2012). "IL18 serum levels in Chagas disease patients according to the HIV status, cardiac phenotypes, parasitemia, and IL 18 −607 and IL 18 −137 genotypes." (PMID 33193300, 2020). "Collectively, IL-6, IL-18, IFN-γ, and IL-10 levels rose with parasitemia, while significant increases in IL-4 were biphasic, with a second peak occurring at day 10 p.i." (PMID 32958528, 2020). "Here, IL-18-dependent Th1 immunity and the likely engagement of IFN-γ in blood-stage parasite killing appear to be sustained for the duration of rising P. yoeliiyoelii 17XNL parasitemia." (PMID 32958528, 2020).
parasitemia (continued). "Mechanistically, we established that T. gondii-mediated activation of the inflammasome and IL-18 were critical to maintain robust CD4+ TH1 IFN-γ responses during parasite infection in the absence of TLR11." (PMID 31194844, 2019). "However, other studies show that NLRP3, ASC, Caspase-1, IL-18, or IL-1 receptor have minor or no impact on parasitemia control or mouse survival." (PMID 30470758, 2018). "Therefore, we hypothesized in the absence of TLR11, IL-18 is required for robust CD4+ TH1-derived IFN-γ responses during parasite infection." (PMID 31194844, 2019).
schizophrenia (20 papers, 2011 to 2025). A major psychotic disorder characterized by abnormalities in the perception or expression of reality. "In agreement with the idea that imbalances of pro- and anti-inflammatory cytokines may contribute to the onset of psychotic symptoms and the progressive loss of brain tissue in schizophrenia, IL-18 has been proposed to be connected to this disorder." (PMID 22913567, 2012). "In particular, five polymorphisms in genes related to the IL-18 pathway, including IL-18 receptor genes, have been associated with schizophrenia and some variants of the IL-18 gene have been recently related to the development of schizophrenia symptoms." (PMID 22913567, 2012). "Furthermore, levels of IL-18 circulating protein are higher in affected patients than in controls and are associated with the psychopathology of schizophrenia." (PMID 22913567, 2012). "In contrast, interleukin-18 (IL-18) has emerged as a putative mediator of the impact of HSV-1 in the context of schizophrenia." (PMID 40806558, 2025). "Elevated IL-18 concentrations have been documented in individuals with schizophrenia, and genetic variations in the components of the IL-18 signalling pathway appear to interact with the serostatus of HSV-1 to influence the risk of disease." (PMID 40806558, 2025). "IL-18, a member of the IL-1 family of proinflammatory cytokines, plays an important role in the Th1 response and, hence, its abnormality in schizophrenia would support the activated macrophage theory." (PMID 33746786, 2021). "Using quantitative RT-PCR, we measured five cytokine mRNAs (IL-1β, IL-2 IL-6, IL-8 and IL-18) from peripheral blood of healthy controls and of people with schizophrenia or schizoaffective disorder (n = 165)." (PMID 28923068, 2017). "As a further indication of the altered modulation of IL-18 system in schizophrenia, we found a positive correlation between total IL-18 and its inhibitor only in SCZ and not in HC." (PMID 22913567, 2012). "As IL-18 and its CNS receptors mediate brain neuroinflammation, modulating homeostasis and behavior, several studies have been conducted to clarify the involvement of IL-18 in schizophrenia." (PMID 33746786, 2021). "The IL-18-binding protein (IL-18BP), whose main role is probably to blunt IL-18 and Th1 activity in order to prevent autoimmune response, may also be of importance in schizophrenia." (PMID 34501305, 2021). "Indeed, in schizophrenia, hippocampal volumes correlate directly with the pro-inflammatory cytokine interleukin-18, while pro-inflammatory IL-1β titres correlate indirectly with Broca’s area volume in a “pro-inflammatory” subgroup of patients." (PMID 29743584, 2019). "The pleiotropic pro-inflammatory cytokine Interleukin (IL)-18 has been proposed to play a role in schizophrenia, since elevated circulating levels of its protein and altered frequencies of genetic variants in its molecular system are reported in schizophrenic patients." (PMID 22913567, 2012). "Therefore, in the present study we analyzed IL-18 and IL-18BP peripheral levels in subjects with schizophrenia diagnosis (SCZ) in comparison to healthy control subjects (HC)." (PMID 22913567, 2012). "In conclusion, these findings indicate that the IL-18 system is perturbed in schizophrenia, supporting the idea that this pro-inflammatory cytokine might be part of a pathway of genetic and environmental components for vulnerability to the disease." (PMID 22913567, 2012). "In conclusion, regardless of whether the IL-18 dysregulation is of genetic, infectious or other origin, our findings strongly suggest that the elevation of IL-18BP found in our SCZ, as well as the whole perturbation of the IL-18 system, might be indeed a specific phenomenon of schizophrenia." (PMID 22913567, 2012).
schizophrenia (continued). "A modest but statistically significant (F = 6.114, df = 1,53, p = 0.017) increase was found for IL6ST mRNA in people with schizophrenia compared with controls, whereas IL8 and IL18 mRNAs (both F < 1.0, df = 1,52/53, p > 0.05) were unchanged." (PMID 31168068, 2021). "We analyzed 77 patients with schizophrenia diagnosis (SCZ) and 77 healthy control subjects (HC) for serum concentration of both IL-18 and its natural inhibitor, the IL-18 binding protein (IL-18BP)." (PMID 22913567, 2012). "As IL-18 acts on the immune system—inducing IFN-γ production from Th1 and NK cells—and as IFN-γ is, in turn, the major activating cytokine of macrophages, the involvement of IFN-γ in schizophrenia has also been studied." (PMID 33746786, 2021). "The early increase in free IL-18, which fades away with age in SCZ, consistently points to the importance of considering age and duration of the illness when discussing the immune-related pathophysiological mechanisms of schizophrenia." (PMID 22913567, 2012). "Previous studies indicate that schizophrenia is paralleled by elevated levels of serum IL-18 without any characterization of the active form of the cytokine." (PMID 22913567, 2012). "Although the IL-18 signaling pathway remains to be fully clarified, its potential role in the pathophysiology of schizophrenia remains speculative rather than proven." (PMID 33746786, 2021). "However, the IL-18 biology in schizophrenia is still unclear and no data are available on the relationship between IL-18 and IL-18BP in affected individuals." (PMID 22913567, 2012). "Of the markers that did not contribute to the final cluster, IL8 and IL18 mRNAs were not significantly different between the subgroups, whereas IL6ST was increased in both the schizophrenia/high and schizophrenia/low immune subgroups compared with the control/low immune subgroup." (PMID 31168068, 2021).